ITGB3 (integrin subunit beta 3)
Diseases named in the same sentence as ITGB3 in open-access papers (continued):
Sharing a sentence is not in itself a finding about the gene and the disease.
asthma (2 papers, 2013 to 2023). "In the present study, we investigated the association of SNPs in ITGB3 with asthma in Chinese Han children using HRM analysis for SNP genotyping." (PMID 23451109, 2013). "The selected SNPs were well genotyped by HRM, and SNP rs3809865 in the 3′ untranslated region (3′UTR) of ITGB3 was found to be strongly associated with asthma (adjusted p = 0.004)." (PMID 23451109, 2013). "To date, few studies have been performed to investigate associations between the ITGB3 gene and asthma in Chinese Han children." (PMID 23451109, 2013). "Given the important roles of environmental exposures in the development of asthma, we evaluated the associations between six SNPs in ITGB3 and asthma in Chinese Han children." (PMID 23451109, 2013). "Our results revealed that rs3809865 was significantly associated with asthma due to its effect on the binding of hsa-mir-124 to ITGB3." (PMID 23451109, 2013). "Several single-nucleotide polymorphisms (SNPs) in the integrin β3 (ITGB3) gene are significantly associated with asthma in Western populations." (PMID 23451109, 2013). "Overall, the findings presented in this study provide new evidence for the association between SNPs in ITGB3 and asthma." (PMID 23451109, 2013). "Our study revealed significant associations between polymorphisms in the ITGB3 gene and asthma risk." (PMID 23451109, 2013). "Thus, it is necessary to identify single nucleotide polymorphisms (SNPs) in the ITGB3 gene associated with asthma in a Chinese population." (PMID 23451109, 2013). "Our results, combined with those of previous reports, suggested that ITGB3 should be considered a true asthma-related gene." (PMID 23451109, 2013). "Previous studies have demonstrated that the ITGB3 gene plays an important role in asthma pathogenesis." (PMID 23451109, 2013). "Recent investigations have suggested that ITGB3 is involved in the pathogenesis of asthma, particularly in early childhood." (PMID 23451109, 2013). "Our results suggest that the αvβ3-mediated T-T cell interactions may also contribute to the roles of αvβ3 in human disease, and that human ITGB3 and ITGAV may represent potential therapeutic targets in asthma." (PMID 36550322, 2023).
autosomal dominant macrothrombocytopenia (2 papers, 2020 to 2025). This syndrome is characterized by congenital thrombocytopenia associated with the presence of large platelets. "Finally, it is worth mentioning that a pathology related to GT is autosomal dominant macrothrombocytopenia caused by heterozygous variants in the ITGA2B and ITGB3 genes." (PMID 41301446, 2025). "Finally, it should be mentioned that a pathology related to GT is autosomal dominant macrothrombocytopenia, caused by heterozygous variants in the ITGA2B and ITGB3 genes." (PMID 41301446, 2025).
Breast Invasive Carcinoma (2 papers, 2005 to 2024). "For this reason, we tested the hypothesis that ITGB3 Leu33Pro heterozygosity and homozygosity have an increased risk of invasive breast cancer." (PMID 15970922, 2005). "Although two later case–control studies did not confirm an increased risk of invasive breast cancer among Leu33Pro homozygotes, certain considerations nevertheless favour the possibility that the ITGB3 Leu33Pro polymorphism may influence risk of invasive breast cancer." (PMID 15970922, 2005).
diabetes (2 papers, 2021 to 2022). "However, ITGB3 has rarely been reported upon in diabetes research." (PMID 36180828, 2022).
Hepatic fibrosis (2 papers, 2025). The presence of excessive fibrous connective tissue in the liver. "In metabolic dysfunction-related steatohepatitis (MASH), ITGB3 promotes hepatic fibrosis via activating hepatic stellate cells, but whether it directly regulates hepatic lipid metabolism through membrane-scaffolding function and the underlying mechanisms remain unclear." (PMID 41360756, 2025).
Hyperglycemia (2 papers, 2020 to 2022). An increased concentration of glucose in the blood. "Db/db mice with pressure ulcers showed an impairment in the molecular regulation of hypoxia-related genes (Hif1a, Flt1, and Kdr), while extracellular matrix encoding genes (Itgb3, Timp1, Fn1, Col4a1) were upregulated by hyperglycemia and lesions." (PMID 35386010, 2022).
hypertrophic cardiomyopathy (2 papers, 2018 to 2025). A condition in which the myocardium is hypertrophied without an obvious cause. "We also observed enrichment in pathways associated with circadian entrainment (e.g., GNG11, GUCY1B1) and hypertrophic cardiomyopathy (e.g., ITGB3, ITGA2B, IL6), suggesting systemic disruptions in PitNET PBMCs." (PMID 41253784, 2025).
Insulin resistance (2 papers, 2025). Increased resistance towards insulin, that is, diminished effectiveness of insulin in reducing blood glucose levels. "In mice, the hepatocyte-specific overexpression of ITGB3 exacerbates diet-induced obesity, insulin resistance, steatosis, and fibrosis, the deletion of ITGB3 alleviates these phenotypes." (PMID 41360756, 2025).
lung fibrosis (2 papers, 2024 to 2025). "Another target gene of miR-382 is the integrin subunit ITGB3, which under normal circumstances promotes the proliferation of pulmonary fibroblasts, thereby causing more pulmonary fibrosis." (PMID 39267761, 2024). "In addition, increased ITGB3 expression and activation is associated with increased LPS-induced lung fibrosis in a murine model." (PMID 40076507, 2025).
lupus (2 papers, 2012 to 2025). "Although lupus in children can have a genetic basis, a mutation in ITGB3 has not been reported to produce monogenetic lupus." (PMID 40264706, 2025).
multiple sclerosis (2 papers, 2025). A progressive autoimmune disorder affecting the central nervous system resulting in demyelination. "PRKCA is involved in immune cell trafficking, and ITGB3 is coding for integrin β3 expression, which is associated with autoimmune conditions including multiple sclerosis." (PMID 40262193, 2025). "The convergence of expression and structural data reframes pleiotrophin–ITGB3 signaling as a central axis of immune–neurovascular integration, underscoring its potential to reshape current strategies for diagnosis and treatment in multiple sclerosis." (PMID 41465519, 2025).
polycystic ovary syndrome (2 papers, 2025). A disorder that manifests as multiple cysts on the ovaries. "Notably, ITGB3 levels were reduced at the embryo implantation site in a mouse model of polycystic ovary syndrome." (PMID 40806633, 2025). "However, emerging evidence suggests that miR-1910-3p may influence infertility, as studies in patients with polycystic ovary syndrome have demonstrated its role in regulating endometrial receptivity through modulation of Integrin beta-3 subunit (ITGB3) and Homeobox A10 (HOXA10) expression." (PMID 40565325, 2025).
pulmonary arterial hypertension (2 papers, 2019 to 2023). Pulmonary arterial hypertension (PAH) is a group of diseases characterized by mean pulmonary artery pressure >20 mmHg and elevated pulmonary arterial resistance leading to right heart failure. "In addition to targeting NLRP3, in a model of pulmonary arterial hypertension (PAH), miR-223 can suppress the expression of the Integrin-β 3 subunit gene (ITGB3) to alleviate the progression of PAH and avoid the dysfunction of pulmonary arterial endothelial cells." (PMID 37465640, 2023).
sarcoma (2 papers, 2025). A usually aggressive malignant neoplasm of the soft tissue or bone. "The effect of ITGB3 or ITGAV shRNA on cell migration and invasion was analyzed using Boyden chamber assays, in which cells were seeded onto a porous membrane that was either uncoated or coated with Matrigel, a sarcoma-derived basement membrane preparation." (PMID 40662366, 2025).
serous ovarian adenocarcinomas (2 papers, 2009 to 2021). "Accordingly, we observed significantly higher expression levels of ITGAV and ITGB3 in human high-grade serous ovarian cancer specimens and ITGAV correlated positively with Wnt5A in metastatic serous type ovarian cancer." (PMID 33723319, 2021). "In this study, we performed an external validation of four potential prognostic biomarkers, ITGB3, CLU, CAPG, and PRAME, in advanced ovarian serous adenocarcinomas." (PMID 19775429, 2009).
thromboembolic diseases (2 papers, 2017 to 2025). "The study indicates that patients with the T/T genotype of ITGA2 and ITGB3 may have an elevated risk of thromboembolism." (PMID 41346645, 2025).
ZIKV infection (2 papers, 2022). "The downregulation of inflammatory genes CCL18, CCL19, CXCL6, CXCL9, IL6R, IL11, IL24, and Integrin Subunit Beta 3 (ITGB3) with ZIKV infection may reflect placental immune tolerance." (PMID 35304593, 2022).
Acidosis (1 paper, 2022). Abnormal acid accumulation or depletion of base. "Additionally, the top seven nodes of the “Acidosis” network were present among the top ten nodes of “Acidosis and Bone metastasis”: COL1A1, COL3A1, COL4A1, COL4A2, ITGB3, THBS2, and ITGA11." (PMID 35159353, 2022).
aortic aneurysm (1 paper, 2024). A ruptured aneurysm located in the wall of the proximal portion of the descending aorta proceeding from the arch of the aorta. "SLC44A2 interacts with neuropilin-1 (NRP1) to activate transforming growth factor β (TGF-β) signaling in an integrin β3–dependent (ITGB3-dependent) manner, which maintains VSMCs’ contractile phenotype and alleviates aortic aneurysm." (PMID 38916960, 2024). "The SLC44A2/NRP1/ITGB3 complex is a major regulator of vascular smooth muscle cell phenotypic switching and a target of lenalidomide in aortic aneurysm treatment." (PMID 38916960, 2024).
Arterial thrombosis (1 paper, 2022). The formation of a blood clot inside an artery. "SNPs in ITGA2 and ITGB3 increase the risk of arterial thrombosis by affecting platelet receptors." (PMID 36362614, 2022).
central nervous system leukemia (1 paper, 2023). Leukemia infiltrating the central nervous system structures. "Firstly, we performed quantitative real-time PCR to assess medullary expression of integrin β3(ITGB3) in T-ALL patients and high ITGB3 expression was relevant with the central nervous system leukemia(CNSL) incidence." (PMID 36944577, 2023).
chronic kidney disease (1 paper, 2021). Impairment of the renal function secondary to chronic kidney damage persisting for three or more months. "We found that ITGB3 was a hub gene in chronic kidney disease (CKD) patients with tubulointerstitial fibrosis." (PMID 34805144, 2021).
cognitive decline (1 paper, 2025). "The biomarkers of platelet activation such as SELP and ITGA2B/glycoprotein IIb‐ITGB3/glycoprotein IIIa are increased in AD patients with faster cognitive decline compared with those with slow cognitive decline." (PMID 39757022, 2025).
demyelinating disease (1 paper, 2021). A broad group of disorders that affect the myelin sheaths that cover the neurons. "Interestingly, research has demonstrated that ITGB3 can regulate expression of matrix metalloproteinase 2 (MMP2), a protein that is critical in the inflammatory response and in demyelinating diseases, such as MS." (PMID 34831441, 2021).
fragile X syndrome (1 paper, 2022). A genetic syndrome caused by mutations in the FMR1 gene which is responsible for the expression of the fragile X mental retardation 1 protein. "To assess the therapeutic potential of regulating Itgb3 gene dosage, we implemented CRISPR activation and compared its efficacy with that of a pharmacological rescue strategy for fragile X syndrome." (PMID 36035754, 2022).
glomerular diseases (1 paper, 2019). "Urokinase plasminogen activator receptor (uPAR) is upregulated in podocytes of glomerular diseases and crucially mediates podocyte injury through integrin β3 (ITGB3)." (PMID 31127093, 2019). "In kidney, uPAR expression is greatly increased in podocytes in glomerular diseases and experimental podocyte injury models, resulting in cytoskeletal injury through activating ITGB3 signaling and downstream Rho GTPases, CDC42 and RAC1, which are crucial for podocyte normal structure and function." (PMID 31127093, 2019).
hemorrhagic stroke (1 paper, 2021). A stroke caused by a bleed on the brain. "The alteration of ITGB1 and ITGB3 expression in cerebral tissue of rats with hemorrhagic stroke was detected by WB." (PMID 33641668, 2021).
Hepatic steatosis (1 paper, 2025). Steatosis is a term used to denote lipid accumulation within hepatocytes. "Pharmacologic inhibition of ITGB3 using cyclic-RGDfk peptide improved serum lipid profiles and hepatic steatosis." (PMID 41360756, 2025). "This study uncovers a previously unrecognized mechanism by which ITGB3 acts as a driver of hepatic steatosis of hepatic steatosis." (PMID 41360756, 2025).
injury (1 paper, 2018). Damage inflicted on the body as the direct or indirect result of an external force, with or without disruption of structural continuity. "We postulated that ITGB3-positive cells would be recruited from the peripheral blood into the liver during Diclofenac-induced liver injury." (PMID 30022949, 2018).
intracerebral hemorrhage (1 paper, 2021). A cerebrovascular disorder characterized by bleeding into one or both cerebral hemispheres including the basal ganglia and the cerebral cortex. "This study explored the relationship between the expression of ITGB1 and ITGB3 in intracerebral hemorrhage (ICH) to analyze their functional and clinical relevance." (PMID 33641668, 2021).
low grade glioma (1 paper, 2019). A grade I or grade II glioma arising from the central nervous system. "CD155 can form the same complex with CD96, CD226, AFDN, ITGAV, ITGB3, and AFDN in low-grade glioma (LGG) and GBM samples derived from the Biological Pathway Ex-change (BioPAX)." (PMID 31377744, 2019).
lymph node metastasis (1 paper, 2021). "In both cohorts, HOXB5 expression positively correlated with CXCR4 and ITGB3 expression, and elevated expression of CXCR4 and ITGB3 positively associated with lymph node metastasis, distant metastasis and advanced AJCC stage." (PMID 33456563, 2021).
membranous nephropathy (1 paper, 2021). "By contrast, no increase in ITGB3 level was detected in the tubule of patients with minimal tubulointerstitial injury, such as minimal change disease (MCD) and membranous nephropathy (MN)." (PMID 34805144, 2021).
meningioma (1 paper, 2020). A generally slow growing tumor attached to the dura mater. "Our study identified integrin beta 3 precursor (ITGB3), alpha V integrin (ITGAV) and alpha M integrin (ITGAM) only in male meningioma samples; these proteins are associated with meningiomas tumorigenesis 7,8." (PMID 32587372, 2020).
Menorrhagia (1 paper, 2023). Prolonged and excessive menses at regular intervals in excess of 80 mL or lasting longer than 7 days. "The results showed that the presence of the A1A1-genotype of the ITGB3 (GP IIIa) gene in adolescents greatly increases the relative risk of menorrhagia by 1.25 times (OR=1.50, p>0.05)." (PMID 36937472, 2023). "We studied genetic and molecular predictors associated with puberty menorrhagia caused by the activity of receptors for glycosylated platelet glycoprotein GP IIIa (integrin beta 3 – ITGB3)." (PMID 36937472, 2023). "Alleles and genotypes of the A1/A2 polymorphic locus of the ITGB3 (GP IIIa) gene as risk factors for puberty menorrhagia." (PMID 36937472, 2023).
metastasis (1 paper, 2022). The spread or migration of cancer cells from one part of the body (where they first appeared) to another. "Moreover, we have validated some previously reported overexpressed genes such as TGFB1, IBSP, MMP9, or ITGB3 in bone metastasis; CRYAB, NRCAM, and SOX2 in brain metastasis; VEGF and IL6 in lung metastasis; and CYP4F3 in liver metastasis." (PMID 34051058, 2022).
metastatic prostate carcinoma (1 paper, 2021). A carcinoma that arises from the prostate gland and has spread to other anatomic sites. "Among the eight integrin subunits analyzed, ITGA5, ITGAV, ITGB1, ITGB3, ITGB4, and ITGB5 were upregulated in the bone compared with the other organs, suggesting that some integrins may confer osteotropic properties on metastatic prostate cancer." (PMID 33514011, 2021).
metastatic tumors (1 paper, 2022). "The relative expression of eight integrins was very low; only ITGB3 showed detectable expression in metastatic tumors compared to the primary lesions; moreover, ITGA2 showed significant negative correlation with the Breslow thickness of the primary tumors." (PMID 36091936, 2022).
migraine (1 paper, 2019). "Also with respect to migraine is ITGB3 which was shown to influence serotonin blood levels, serotonin being previously implicated in migraine etiology." (PMID 31026304, 2019).
migraine headache (1 paper, 2019). "In addition, a migraine headache pathway of related proteins also appears in this comparison, most notably ITGB3, KCNK18, NOTCH4, and LRP1 which could be interacting with glutamate receptors." (PMID 31026304, 2019).
myeloid tumor (1 paper, 2021). "Given that in JAK2V617F-positive cMPN patients, the transcription level of the ITGB3 gene is much higher than that of normal samples, we suspected that a similar phenomenon may be observed in the myeloid tumor cell lines." (PMID 34738870, 2021). "Furthermore, the evaluation of ITGB3 transcription and translation levels in a variety of myeloid tumor cell lines revealed that in cell model of JAK2V617F-positive cMPN, the levels of ITGB3 were also far higher than that of negative control cell lines." (PMID 34738870, 2021).
nodular melanoma (1 paper, 2022). "The relative expression of the eight tested integrins was low, with only the expression of ITGB3 being detectable in nodular melanoma (Medianlog2 = 1.274)." (PMID 36091936, 2022).
ovarian adenocarcinoma (1 paper, 2009). An adenocarcinoma that arises from the ovary. "The clinical outcome of patients with advanced ovarian adenocarcinoma is difficult to predict at an individual level, and ITGB3 could be a complementary potential biomarker for patients with serous tumours." (PMID 19775429, 2009). "Therefore, the use of ITGB3 as a biomarker may only have clinical relevance in ovarian adenocarcinomas." (PMID 19775429, 2009). "Finally, the function of ITGB3 as a biomarker in ovarian adenocarcinoma may be influenced by other factors in the tumours." (PMID 19775429, 2009).
pituitary adenoma (1 paper, 2023). "SLC2A1, CLDN4, LAMC2, S100A4, and ITGB3 were significantly correlated with the invasiveness of pituitary adenoma (P<0.05)." (PMID 36936141, 2023).
preeclampsia (1 paper, 2024). Preeclampsia is a hypertensive disorder of pregnancy that is characterized by new-onset hypertension with proteinuria presenting after 20 weeks of gestation, and depending on mild or severe forms may initially present with severe headache, visual disturbances, and hyperreflexia. "The expression of ITGB3 is widely associated with preeclampsia." (PMID 39721996, 2024). "The results revealed that the expression of ITGB3 in the placenta of pregnant women with preeclampsia was significantly lower than those with normal pregnancy." (PMID 39721996, 2024). "Moreover, downregulation of ITGB3 appears to play a pivotal role in the pathogenesis of preeclampsia, including its inception, progression, and progression." (PMID 39721996, 2024).
proliferative diabetic retinopathy (1 paper, 2016). Advanced retinopathy due to diabetes mellitus characterized by the formation of new vessels in the retina. "ITGB3 plays a prominent role in the angiogenic response in proliferative diabetic retinopathy." (PMID 27781209, 2016).